IL10 (interleukin 10)
Diseases named in the same sentence as IL10 in open-access papers (continued):
Sharing a sentence is not in itself a finding about the gene and the disease.
migraine (39 papers, 2011 to 2025). "A second study in rats highlighted liraglutide ́s role in promoting the release of IL-10, an anti-inflammatory cytokine that was effective in relieving migraine-associated pain." (PMID 38997662, 2024). "Consistent with this view, we found that the stimulation of meninges with the P2X7 agonist BzATP enhanced the release of the pro-inflammatory TNFα and Il-10, which are both implicated in migraine pathology." (PMID 35614095, 2022). "Furthermore, higher IL-10 plasma levels have been observed during migraine attacks; on the other hand, some studies showed that HP infection is associated with increased levels of IL-12 and IL-10." (PMID 32054443, 2020). "Despite the currently incomplete definition of the exact pathophysiology of migraine, cytokine-related genes, such as tumor necrosis factor (TNF), interleukin-1β (IL-1β) and IL-10, are known genetic candidates contributing to the predisposition towards migraine development." (PMID 24959879, 2014). "For example, patients with H. pylori infection exhibit elevated levels of IL-10, a cytokine that is similarly increased during migraine attacks." (PMID 39967603, 2025). "It remains possible that inadequate levels of IL-10 permit unchecked inflammation in migraine – an area for further research." (PMID 41377228, 2025). "Compared with the control group, the blood levels of IL-1β and IL-10 were increased in migraine patients." (PMID 39416954, 2024). "It has also been confirmed that the interictal level of IL-10 in migraine patients decreases, indicating that IL-10 is closely related to migraine remission." (PMID 37450927, 2024). "A later study further pointed out that IL-10 signaling pathways in trigeminal ganglions are potential targets for migraine treatment." (PMID 37450927, 2024). "A case-control study investigating newly diagnosed migraine patients revealed significantly higher serum IL-1beta and IL-6 concentrations, while the IL-10 serum levels were lower compared to those of healthy controls." (PMID 36835524, 2023). "Other cytokines, including IL-10 and tumor necrosis factor alpha (TNF-α), have shown associations with migraine." (PMID 37755358, 2023). "A clinical trial demonstrated that IL-10 serum levels were higher during migraine attacks versus during the interictal period and in healthy controls." (PMID 36835524, 2023). "Most studies have reported decreased levels of IL-10 in the interictal period in migraine patients compared to controls." (PMID 37176049, 2023). "They did find a trend for the pro-inflammatory cytokines TNF-α and IL-6 to be higher, and the anti-inflammatory cytokine IL-10 to be decreased, in the interictal period in migraine compared to healthy controls." (PMID 37016284, 2023). "The most relevant cytokines related to migraines include IL-1, IL-2, IL-4, IL-6, IL-10, TNF-α, and TGF-β." (PMID 35896985, 2022). "Proinflammatory cytokines, such as interleukin (IL)-1β, IL-6, and tumor necrosis factor-alpha (TNF-α), as well as anti-inflammatory cytokines, such as IL-10, are elevated in patients with migraine and are suggested to play a role in migraine." (PMID 36362765, 2022). "In migraine patients, increased plasma levels of IL-10, TNFα, and IL-1 beta have been observed after a migraine attack and some studies have linked migraine attacks to local inflammatory events." (PMID 34948222, 2021). "sCD40L stimulates the production of proinflammatory cytokines (IL-1, IL-6, IL-8, IL-10, TNF), which are pain mediators and are suggested to be implicated in neurovascular inflammation resulting in migraine pain." (PMID 33020432, 2020). "The specific expression patterns of MCP-1, IL-10, TGF-beta, and other cytokines have also been linked with migraine disease development." (PMID 33178826, 2020). "On the other hand, the levels of the anti-inflammatory cytokine IL-10 have been found to be either unaltered or reduced in migraine patients as compared to healthy controls." (PMID 31331109, 2019).
migraine (continued). "By increasing IL-10 secretion and modulating both innate and adaptive immunity, Faecalibacterium prausnitzii could help attenuate neuroinflammation relevant to migraine pathophysiology." (PMID 40175732, 2025). "TNF alpha, IL-6, IL1 beta and IL10 were found to be increased during migraine attacks." (PMID 21331754, 2011). "Therefore, the IL-10/IL-10R pathway may be a promising way to inhibit migraine pain symptoms by regulating crosstalk between microglia and astrocytes." (PMID 37450927, 2024). "Multiple linear regression models show that migraines are positively correlated with TNF-α and negatively related to IL-10." (PMID 37450927, 2024). "A clinical study of migraine patients revealed that the plasma levels of TNF-alpha, IL-1beta, and IL-10 were significantly higher ictally versus interictally." (PMID 36835524, 2023). "For example, butyrate enhances the release of the anti-inflammatory cytokine IL-10 and sodium butyrate treatment attenuates pain attacks in a mouse model of nitroglycerine (NTG)-induced migraine." (PMID 36457577, 2022). "One study showed that migraine patients have higher levels of interleukin 1-beta (IL1-β) and interleukin-6 (IL6), and lower levels of interleukin-10 (IL10) compared to healthy control patients." (PMID 35432179, 2022). "Interleukin (IL)-1β, IL-6, IL-10, and tumor necrosis factor (TNF)-α levels are elevated in the blood during or early in the migraine pain period compared to the non-migraine pain period." (PMID 34444772, 2021). "Therefore, based on the available shreds of evidence, it can be hypothesized that elevated IL-17 and IL-6 and on the other hand, reduced TGF-β and IL-10 levels might be involved in migraine pain pathophysiology certainly through exacerbating inflammatory responses." (PMID 33653409, 2021). "In the IS-induced mouse model, A1 astrocytes are generated and sustained, which may lead to migraines by regulating the release of CC-chemokine ligand 7 (CCL7), CC-chemokine ligand 12 (CCL12), and IL-10." (PMID 37450927, 2024). "Furthermore, we identified genome-wide pleiotropy between migraine and lower levels of IL19, an anti-inflammatory cytokine that belongs to the IL10 cytokine subfamily." (PMID 35546551, 2022). "In our ex vivo preparation, pro-inflammatory cytokines (i.e., IL-6, IL-10, MCP-1, TNFα, IL-12p70, and IFNγ) are released and detectable already at basal conditions, confirming the local source of inflammatory stimuli that can trigger migraine." (PMID 35614095, 2022). "CD4+ Th cells produce IL-10, a primarily anti-inflammatory cytokine which also activates B cells, and plasma levels of IL-10 have been shown to be increased during migraine attacks in patients with migraine without aura, suggesting systematic inflammation in migraine pathogenesis." (PMID 39407099, 2024). "During migraine attacks, there are elevated serum levels of IL-10 and TNF-α; moreover, between attacks, TNF-α levels in plasma are higher in children who suffer from migraine compared to those who do not." (PMID 37755358, 2023). "Interestingly, a result not seen in migraine is that the inflammatory cytokine MCP-1 correlates with the anti-inflammatory cytokines IL-1ra, TGF-b1, and IL-10 in episodic TTH." (PMID 37176049, 2023).
intestinal inflammation (38 papers, 2010 to 2025). "Impaired IL-10 signaling is involved in the pathogenesis of IBD, and mice deficient in IL-10 are known to develop spontaneous intestinal inflammation." (PMID 36077306, 2022). "B cells expressing high levels of CD1d and CD5 have been linked to the regulation of chronic intestinal inflammation, experimental arthritis, and T cell-mediated inflammation through IL-10 secretion." (PMID 23071588, 2012). "Here, we originally identified IL-10−/− female mice as more prone to developing intestinal inflammation, with an increase in fecal miR-21, and dysbiosis with more detrimental characteristics compared to males." (PMID 37373511, 2023). "We also found increased levels of IL‐10 mRNA in all the forms of colonic and ileal intestinal inflammation, as previously found in IBD27, 28 and microscopic colitis." (PMID 36169258, 2022). "Using a mouse model of DSS-induced intestinal inflammation, we observed the changes in intestinal microbiota and metabolites, and the expression of AhR, interleukin-10 (IL-10), and transforming growth factor beta (TGF-β) after FMT." (PMID 30197631, 2018). "By promoting the secretion of thymic stromal lymphopoietin, epidermal growth factor, IL-10, IL-25, and transforming growth factor-β1 by intestinal epithelial cells, Gal1 can inhibit experimental intestinal inflammation." (PMID 28086216, 2017). "Moreover, TLR4 has been identified as being a major driver of inflammation in C. jejuni-infected IL-10−/− mice and the present study found the gastroenteritis seen in infected Sigirr−/− mice is almost completely TLR4 dependent." (PMID 25033044, 2014). "Recently, anti-inflammatory probiotic properties were screened and distinguished according to their ability to preferentially induce IL-10 or IL-12 secretion, and strains leading to higher IL-10/IL-12 ratio were very potent in reducing TNBS-mediated intestinal inflammation." (PMID 21808650, 2011). "Animal studies have suggested that lycopene could not only suppress the expression of pro-inflammatory factors like IL-1β, IL-6, IL-8 and TNF-α, but also stimulate the production of anti-inflammatory cytokines (such as TGF-β, IL-10), so as to reduce intestinal inflammation." (PMID 37608273, 2023). "Il-10-secreting intestinal ILCreg also secrets TGF-β, which amplifies ILCreg expansion by autocrine, and exerts anti-inflammatory function during intestinal inflammation." (PMID 32235696, 2020).
lung disease (38 papers, 2010 to 2025). "Evidence linking IL-10 variants to neonatal lung disease is limited; however, differences in IL-10 expression have been described in preterm infants with RDS, particularly in relation to BPD." (PMID 40941746, 2025). "After further adjustment for traditional and HIV-related risk factors for lung disease, as well as cytokines (IL-1β, IL-10), the gut microbial dysbiosis index was independently associated with rapid lung function decline." (PMID 40557154, 2025). "Overall, data suggests the therapeutic potential of SAHA (or other specific HDAC inhibitors) in rescuing Pa-LPS induced CF-lung disease via partial induction of IL-10 (T-reg associated cytokine), while inhibiting neutrophil influx." (PMID 29301535, 2018). "In lung disease, high levels of IL-10 and IL-13 have been found to cause T- and B-cell–rich inflammatory response, subepithelial fibrosis, and mucus metaplasia with goblet cell hyperplasia and mucin hypersecretion, all of which may be the result of IL-10–induced IL-13 production." (PMID 38508309, 2024). "In light of these opportunities and challenges, this review aims to provide a comprehensive overview of current IL-10 delivery systems and to highlight strategies for their optimization to facilitate clinical translation in pulmonary diseases." (PMID 41312367, 2025). "This article provides a concise overview of the immunomodulatory functions of IL-10 and its therapeutic potential in a variety of lung diseases." (PMID 41312367, 2025). "MSC-EVs have been used in several studies for IL-10 delivery, making exosome-mediated IL-10 delivery for pulmonary diseases a promising approach." (PMID 41312367, 2025). "Conversely, IL‐10, an anti‐inflammatory cytokine, is reduced in patients with pulmonary diseases and is negatively correlated with disease severity and progression." (PMID 40330764, 2025). "These IL-10-based therapies for pulmonary diseases can be broadly categorized into two main strategies: prolonging the half-life of exogenous IL-10 and enhancing the secretion of endogenous IL-10." (PMID 41312367, 2025). "This choice was made based on reports showing that exogenous delivery of IL‐10 ameliorates different lung diseases and because the lung is a challenging organ due to its reduced microbiome size." (PMID 36598022, 2023). "Subsequent production of the anti-inflammatory cytokine IL-10 by T cells compromises microbial control, leading to severe lung disease." (PMID 35768411, 2022). "The regulatory cytokine IL-10 is involved in various lung diseases, like asthma, allergic airway disease (AAD), chronic obstructive pulmonary disease (COPD), and pulmonary infections." (PMID 33979348, 2021). "The cytokine IL-10 is a critical immune regulator and was shown, for example, to limit pathology during various lung diseases." (PMID 33979348, 2021). "These contradictory effects of IL-10 in lung diseases reveal a different perspective toward efferocytosis in infectious diseases." (PMID 32346605, 2020). "Next, we evaluated the changes in levels of IL-10, a regulatory T cell (CD4 + FoxP3+ T-regs)-associated immunosuppressive cytokine, as T-reg dysfunction is implicated in chronic CF-lung disease pathogenesis." (PMID 29301535, 2018). "The progression of lung disease was monitored by quantifying changes in inflammatory markers (NFκB), cytokines (IL-6/IL-10), neutrophil activity (MPO, myeloperoxidase and/or NIMP-R14) and T-reg numbers." (PMID 29301535, 2018). "Cytokines such as TNF-alpha, IL-6, and IL-10, modulate the recruitment and the activation of leukocytes in lung diseases." (PMID 26569396, 2015). "Our data indicate that IL-10 plays a significant role in preventing the development of pulmonary disease during chronic schistosomiasis and that it does so via a mechanism that is unrelated to Th2 cell hyporesponsiveness." (PMID 22291593, 2012).
lung disease (continued). "From studies in mouse models of lung disease, which have shown that IL-10 impedes neutrophil recruitment, thereby hindering the clearance of bacterial infections, we can infer that IL-10 likely negatively affects neutrophil behavior in CLL; however, the mechanisms by which it does so are unclear." (PMID 40909277, 2025). "By addressing the remaining challenges, IL-10-based treatments have the potential to move from promising experimental strategies to effective clinical solutions for patients suffering from debilitating lung diseases." (PMID 41312367, 2025). "It suggests a close relationship between B cells and IL10 in lung disease progression." (PMID 39896814, 2024). "Our findings suggest that certain immune mediators, such as IL‐10, may have utility in distinguishing healthy adults from those with lung disease, but these results will need to be confirmed in a larger prospective study designed to test this hypothesis." (PMID 36780897, 2023). "IL‐10 can be used as treatment of a wide range of pulmonary diseases." (PMID 36598022, 2023). "Likewise, IL-10 has similar anti-inflammatory effects and shows improvement in most lung diseases, whereas it promotes infection in Klebsiella pneumoniae." (PMID 32346605, 2020). "Interestingly different gene combinations were associated with the less severe (IL-6; Pmd) or more severe form (IL-10; Pad) of pulmonary disease." (PMID 22140472, 2011). "Because SOCS3 has been proposed as a mechanism of IL-10–mediated protection against inflammatory processes in other models of lung disease, we asked whether SOCS3 was differentially expressed in Il10−/− and Il10+/+ mice." (PMID 20826374, 2010). "All of these cytokines, TNF‐α, IL‐10, and IFN‐γ, are targets for treating different pulmonary diseases; for example, administration of recombinant human IFN‐γ results in favorable respiratory outcomes in patients exposed to sulfur mustard." (PMID 40330764, 2025). "Treg secretes immunosuppressive factors such as IL-10 and TGF-β, which are involved in a variety of chronic inflammation-mediated lung diseases." (PMID 39108691, 2024). "In the SR-triggered farmer's lung disease model, Foxp3+ CD4+ T cells are the majority of the IL-10-producing LAG3+CD49b+ T cell subset in the lungs, however, there are similar percentages of Foxp3− CD4+ and CD8+ T cells (16% each)." (PMID 30510554, 2018). "Also in NTM patients with nodular bronchiectasis, it was suggested that susceptibility to pulmonary disease may reflect low IL-17 and high IL-10 responses, rather than a Th1 deficiency." (PMID 28182785, 2017). "It has been shown that, in comparison to healthy individuals, the patients with mild, moderate, or advanced pulmonary disease were having enhanced levels of IFN-γ, IL-2, IL-4, and IL-10." (PMID 27819024, 2016). "The present study revealed that IL-8, IL-10, IL-18, TNF-α, and IP-10 are significantly correlated with pulmonary disease activity and global disease activity." (PMID 24800252, 2014). "IL-10 is a regulatory cytokine involved in limiting the inflammatory response during NTM infection; in particular, IL-10 inhibits the secretion of IFN-γ and IL-12 in patients with MAC lung disease." (PMID 25295870, 2014). "However, the patients with moderate and advanced pulmonary disease were having enhanced levels of cytokines IL4 and IL-10 in contrast to mild disease patients." (PMID 27819024, 2016). "LNs offer advantages such as high stability, large drug loading capacity, and non-toxicity, and although some LN-based platforms have been developed to enable targeted delivery to the lung, no studies have yet explored their use in IL-10 delivery or pulmonary disease treatment." (PMID 41312367, 2025). "Plasma levels of IL-6, tumor necrosis factor, IL-10, and IL-1 receptor antagonist remained low after 1 h of IMV in 39 adults with no previous lung disease." (PMID 35844745, 2022).
lung disease (continued). "Furthermore, serum levels of IL-10 significantly increased while TNF-and ESR values substantially decreased from day 0 to day 60 of ATT in patients with cavitary TB but not in those with non-cavitary lung disease." (PMID 27494953, 2016).